IRF8 (interferon regulatory factor 8)
Diseases named in the same sentence as IRF8 in open-access papers (continued):
Sharing a sentence is not in itself a finding about the gene and the disease.
endometriosis (1 paper, 2022). The growth of functional endometrial tissue in anatomic sites outside the uterine body. "In recent publications, IRF8 positive cells were reported to be increased during the proliferative phase of the menstrual cycle in the endometrium of women with endometriosis." (PMID 35918717, 2022).
female infertility (1 paper, 2022). Diminished or absent ability of a female to achieve conception. "Similarly, UPF3B, IRF8, and PSMB1 were the top 3 hub genes identified with the female infertility network." (PMID 35918717, 2022).
granulocytosis (1 paper, 2020). "Similar to Icsbp/Irf8−/− mice, we found exaggerated Alum-induced granulocytosis without steady state resumption between episodes." (PMID 32080344, 2020).
Granuloma (1 paper, 2013). A compact, organized collection of mature mononuclear phagocytes, which may be but is not necessarily accompanied by accessory features such as necrosis. "H&E staining of lung sections at day 15 p.i. evidenced few granulomas in healthy lung parenchyma of both WT-B6 and IRF-8−/− mice, albeit those of deficient mice appeared less organized with a increased number of mononuclear cells infiltrated." (PMID 23717393, 2013). "Moreover, our data disclose the prominent role of IRF-8 at late stages of Mtb infection, when the massive recruitment of neutrophils and the loss of T cells in both LS and granulomas define the poor outcome of TB in deficient mice." (PMID 23717393, 2013). "Our data define IRF-8 as an essential factor for the maintenance of proper immune cell recruitment in granulomas and LS required to restrain Mtb infection." (PMID 23717393, 2013). "Of interest, at this time point IRF-8−/− granulomas exhibited high levels of CCL19 in the outer layers." (PMID 23717393, 2013). "In contrast, while in WT-B6 granulomas numerous FDC were detected in a well-localized reticulum, few FDC were identified interspersed within IRF-8−/− granulomas." (PMID 23717393, 2013). "Our data show that truthful organization of granulomas and pulmonary LS are processes tightly controlled by IRF-8, since they occur properly in lungs of Mtb-infected immunocompetent but not in IRF-8-deficient mice." (PMID 23717393, 2013). "Importantly, the unbalanced presence of certain immune cells in the lungs of IRF-8−/− mice differently reflects their distribution within LS and granulomas throughout TB." (PMID 23717393, 2013). "Nonetheless, elevated amounts of 7/4+ neutrophils persistently populated IRF-8−/− granulomas." (PMID 23717393, 2013).
Hepatic steatosis (1 paper, 2025). Steatosis is a term used to denote lipid accumulation within hepatocytes. "Mice with adeno-associated virus-mediated IRF8 overexpression exhibited hepatic steatosis due to up-regulated peroxisome proliferator-activated receptor γ (PPARγ) expression and increased fatty acid uptake and lipogenesis." (PMID 40083324, 2025). "Consistent with the mitigation of hepatic steatosis, glucose tolerance also improved after interfering with IRF8, as shown by IPGTT." (PMID 40083324, 2025).
histiocytic neoplasm (1 paper, 2026). Histiocytic tumors are a heterogeneous group of tumors and tumorlike masses commonly associated with histologically identical extracranial lesions. "NPM1 mutation-specific antibodies should be integrated into the diagnostic panels for MS or LC, while IRF8 and PU.1 are not recommended as they cannot distinguish MS from histiocytic neoplasms." (PMID 41781345, 2026).
Hypertension (1 paper, 2024). The presence of chronic increased pressure in the systemic arterial system. "Two DEGs (Irf8 and Smad9) are associated with hypertension and encode TFs (both are downregulated)." (PMID 38928385, 2024).
injury (1 paper, 2022). Damage inflicted on the body as the direct or indirect result of an external force, with or without disruption of structural continuity. "Previous studies have shown that overexpression of IRF8 can enhance cytokines in microglia, and knockdown of IRF8 can attenuate mechanical allodynia caused by nerve injury." (PMID 36713369, 2022).
ischemic stroke (1 paper, 2025). A stroke disorder caused by obstruction of blood flow to the brain, due to thrombotic (local blood clot formation) or embolic (due to a blood clot or other material traveling from another site) event. "In addition, other paralogs of IRF6, such as IRF4, IRF5, IRF8, and IRF9, have been linked to neuronal survival following ischemic stroke." (PMID 40149423, 2025).
keratoconus (1 paper, 2022). A degenerative, structural disorder of the eye, characterized by a cone-shaped protrusion of the cornea. "In addition to intracerebral calcifications, the patient described here also had other brain lesions and signs of developmental features (including mid facial hypoplasia and keratoconus) that had not been described in other patients with AR complete IRF8 deficiency." (PMID 35338423, 2022).
Legionella infection (1 paper, 2020). "Interestingly, although the effects of IRF8 were demonstrated at steady state, Irf8 is induced upon Legionella infection and could participate in the NAIP/NLRC4-dependent response against this flagellin-expressing pathogen." (PMID 33138274, 2020).
leprosy (1 paper, 2021). Leprosy is a chronic infectious disease affecting primarily the skin and peripheral nervous system. "A similar study in Vietnamese leprosy patients showed upregulation of IFN-γ pathway genes including IFN-γ, STAT1, IRF8 and IL-12 after stimulation of PBMCs by sonicated antigens." (PMID 34993156, 2021).
leukocytosis (1 paper, 2023). "The Irf8−/− group exhibited distinct hepatosplenomegaly and pale appearance of femurs, indicating leukocytosis, erythrocytopenia and infiltration in multi‐organs, while the Irf8+/+ group showed leukemogenesis to a less extent." (PMID 36478193, 2023).
lupus nephritis (1 paper, 2021). Glomerulonephritis in the context of systemic lupus erythematosus. "Further analysis revealed that HLA-DPA1, IL10RA, and IRF8 were differentially expressed in different pathological staging samples of lupus nephritis." (PMID 34692653, 2021).
metastatic melanoma (1 paper, 2025). A melanoma that has spread from its primary site to another anatomic site. "Multiplex immunofluorescence staining of sentinel lymph node tissues from metastatic melanoma patients confirmed protein-level co-expression of IRF4 with IRF8 in CD11C + CCR7+ mregDCs." (PMID 40890106, 2025).
nephritis (1 paper, 2019). Inflammation of renal tissue. "Moreover, separate analysis of DCs subpopulations, revealed that only in mDCs from patients with severe nephritis, the level of IRF8 transcript was increased, whereas two remaining patient groups (mild and moderate LN), showed inverted tendency." (PMID 31507612, 2019).
non-alcoholic steatohepatitis (1 paper, 2025). "It remains unclear whether IRF8 contributes to non-alcoholic steatohepatitis, the advanced stage of NAFLD." (PMID 40083324, 2025).
non-small cell lung carcinoma (1 paper, 2014). A group of at least three distinct histological types of lung cancer, including non-small cell squamous cell carcinoma, adenocarcinoma, and large cell carcinoma. "The aim of the present study was to investigate the aberrant methylation and altered expression of the interferon regulatory factor 8 (IRF8) gene in non-small cell lung cancer (NSCLC)." (PMID 25120651, 2014).
ovarian carcinoma (1 paper, 2026). A malignant neoplasm originating from the surface ovarian epithelium. "Although IRF8 is linked to favorable outcomes in some cancers, our findings suggest that the IRF8-TAM gene signature predicts immune dysfunction in ovarian cancer, highlighting the complex and context-dependent role of IRF8 within the TME." (PMID 41596598, 2026). "Among the genes we identified in this study, IL7R, IRF8, PTPRC, and NSG1 have not been thoroughly explored or recognized for their relevance in ovarian cancer recurrence in previous studies." (PMID 41596598, 2026).
overnutrition (1 paper, 2022). An imbalanced nutritional status resulting from excessive intake of nutrients. "Compared with the irf8+/+ control, these fish produced a similar number of β cells during development and showed similar levels of β cell neogenesis in response to one session of overnutrition (Maddison and Chen, 2012)." (PMID 36001973, 2022). "Unlike the irf8+/+; zMIR controls, irf8−/−; zMIR fish showed no overnutrition-induced β cell loss at 72 hpt." (PMID 36001973, 2022).
Pneumocystis infection (1 paper, 2010). "Among the genes that were affected by dexamethasone and further affected by Pneumocystis infection, Mgst1 and Hspa1b genes were down-regulated, while Cd14, Irf8, Il1b, Cxcl13, Cxcr4, Fn1, Irf1, Cd74, S100a9, and Spp1 genes were up-regulated in all four groups." (PMID 20377877, 2010). "Both Irf-1 and Irf-8 genes were down-regulated by dexamethasone (-1.52 and -1.61, respectively) but up regulated by Pneumocystis infection (4.45 and 2.13 fold, respectively)." (PMID 20377877, 2010).
psychosis (1 paper, 2021). "Our findings suggest that alterations to activity of the IRF8/IRF1 regulome may underlie the IFN-γ signature changes and drive the monocyte phenotype shifts observed in individuals with psychosis." (PMID 34054608, 2021).
pulmonary sarcoidosis (1 paper, 2022). Sarcoidosis affecting the lung parenchyma. "We indeed found that essentially all of the IL12B expression was from a similar population of IRF8+XCR1+BATF3+ cDC1s in pulmonary sarcoidosis." (PMID 35668129, 2022).
rectal cancer (1 paper, 2017). A primary or metastatic malignant neoplasm that affects the rectum. "In particular, the authors demonstrated that the IRF2 mutational status is associated with both colon and rectal cancer, whereas mutations in other genes involved in IFN signaling pathway were uniquely associated with colon (IFN-γ and IRF3) or rectal cancer (IFNGR1, IFNGR2, IRF4, IRF6, and IRF8)." (PMID 28798748, 2017).
renal dysfunction (1 paper, 2019). "In addition, we found that IRF8 expression was higher-expressed in the peripheral blood lymphocyte (PBL) in renal dysfunction w/o rejection than those with normal kidney function or with acute rejection in post-transplantation recipients." (PMID 31343413, 2019).
Salmonella Infections (1 paper, 2023). Infections with bacteria of the genus SALMONELLA. "The most important TF for predicting the response to Salmonella infection was IRF8, followed by MBD2 and ZBT14." (PMID 37073532, 2023).
skin aging (1 paper, 2025). The gradual irreversible changes in structure of skin that occur as a result of the passage of time.. "Addressing this gap requires additional basic studies to elucidate these molecular connections, potentially paving the way for therapeutic strategies, such as targeted inhibition of IRF8-mediated cellular senescence to combat skin aging." (PMID 40759632, 2025). "The original study primarily attributed IRF8-mediated senescence to SASP as the key driving force of skin aging, but this explanation remains simplistic." (PMID 40759632, 2025).
steatosis (1 paper, 2026). Increased lipid within the cytoplasm of cells. "Additional evidence demonstrates that IRF5, IRF6, and IRF8 are also play key roles in hepatocytes: IRF5 mediates Fas-induced apoptosis, IRF6 suppresses PPARγ to reduce lipid accumulation, and IRF8 aggravates steatosis through a BMAL1/PPARγ axis." (PMID 41614922, 2026).
tumor (200 papers, 2010 to 2026). "In the context of tumors, IRF-8 has garnered attention for its dual role, acting both as a tumor suppressor and, in some cases, being associated with tumor promotion, depending on the cancer type and the microenvironment." (PMID 41315179, 2025). "The overexpression of IRF8 has been shown to inhibit the growth of tumor-induced MDSCs in mouse models, while IRF8 deficiency facilitates granulocyte expansion." (PMID 41368628, 2025). "Previous studies have shown that tumor-associated macrophages present cancer cell antigens and induce T-cell dependent IRF8, which promotes tumor growth." (PMID 40496561, 2025). "In contrast, studies in tumor-bearing mice have shown a more pronounced loss of IRF-8 in G-MDSCs compared to M-MDSCs." (PMID 40725182, 2025). "Research has found that tumor-associated macrophages expressing the transcription factor IRF8 contribute to TEX in cancer." (PMID 40496561, 2025). "Specifically, type 1 dendritic cells (DC1s) and the tumour-associated macrophages (TAMs) require and express IRF8." (PMID 38792023, 2024). "We observed similar effects following co-injection of gRNAs targeting irf8, suggesting that increased p53EPS tumor initiation following Irf gene knock-down is a consequence of irf7 and irf8 loss-of-function in the TME." (PMID 39052000, 2024). "IRF8 used to be considered a transcription factor associated with cDC1 differentiation and was recently regarded as a key TF in TAMs for presenting tumour cell antigens and driving T-cell exhaustion." (PMID 38906852, 2024). "As expected, loss of IRF8 function in the CMS4.K79E cell line significantly decreased tumor cell sensitivity to RSL3-induced cell death." (PMID 36672246, 2023). "To restore IRF8 expression in tumor cells, we designed and synthesized codon usage-optimized IRF8-encoding DNA to generate IRF8-encoding plasmid NTC9385R-mIRF8." (PMID 36672246, 2023). "IRF8 expression by tumor-associated macrophages (TAMs) was negatively associated with tumor stage and positively correlated with prognosis in ccRCC patients." (PMID 37182129, 2023). "IRF8.KO tumor cells acquire resistance to intrinsic ferroptosis induction and IRF8-deficient tumor cells also exhibit decreased ferroptosis in response to tumor-specific CTLs." (PMID 36672246, 2023). "In line with this, the observed CCR2+ monocytes expressed Irf8, which is associated with the induction of T cell exhaustion, further promoting tumor growth." (PMID 37849753, 2023). "Consistent with this phenomenon, lipid nanoparticle-mediated IRF8-encoding plasmid DNA therapy significantly increased tumor cell death and suppressed established tumor growth." (PMID 36672246, 2023). "Silenced IRF8 expression in both tumor cells and tumor-induced myeloid cells by DNA methylation and H3K9me3 deposition at the Irf8 promoter are likely major mechanisms underlying OPN elevation in cancer patients and tumor-bearing mice." (PMID 36078039, 2022). "High levels of IRF8 were detected in tumor-associated cDC1s and its downregulation impairs the proper differentiation from the progenitors." (PMID 36230990, 2022). "IRF8 is essential for myelopoiesis and loss of IRF8 expression or function results in accumulation of CD11b+Gr1+ IMCs that phenotypically and functionally resemble tumor-induced MDSCs." (PMID 36078039, 2022). "Tumor growth in mice was associated with the selective expansion of low-IRF8 granulocyte progenitors (GPs)." (PMID 36078039, 2022). "Studies revolving around a loss of IRF8 have elucidated ways in which IRF8 helps facilitate Fas-mediated apoptosis and resulting in tumor immune sensitivity." (PMID 36078039, 2022). "A major phenotype of IRF8 knock out (IRF8 KO) mice or mice with IRF8 deficiency is accumulation of CD11b+Gr1+ IMCs that phenotypically and functionally resembles tumor-induced CD11b+Gr1+ myeloid-derived suppressor cells (MDSCs)." (PMID 36078039, 2022).
tumor (continued). "IRF8 was associated with depleted CD8+ T cells in the GC.The transcription factor RBPJ was overexpressed in the tumor-infiltrating Tregs.DC cells expressed more inhibitory receptors in GC tissues, for example, FTL and IL8." (PMID 35785171, 2022). "In these studies, tumor-bearing mammary fat pads underwent ASC population shifts from ASC2 to ASC1 in tumor-bearing mice as well as changes in macrophage expression patterns linked to inflammatory responses, such as increased Trem2 and Irf8." (PMID 33088423, 2020). "These neutrophils harbor an immature myeloid phenotype and, interestingly, have been shown to inhibit T cell activation; therefore, these IRF8-deficient myeloid cells seemed to mirror tumor-induced PMN-MDSCs at multiple levels." (PMID 32983128, 2020). "When the distance was extended to within 10–20 μm, the CD68+IRF8+ macrophages (47%) remained the major population associated with tumor cells." (PMID 31477692, 2019). "As a member of the interferon regulatory factor family, IRF8 is needed for the development of immune cells and is often regarded as a tumor suppressor gene since a loss of function is associated with increased metastatic potential." (PMID 31684858, 2019). "Interferon regulatory factors (IRF) are transcription factors comprising of a large number of isoforms, among which IRF-1 and IRF-8 (or ICSBP) are associated with a vast range of host responses to infection and tumor growth." (PMID 30701020, 2018). "Mice deficient for both PU.1 and IRF8 developed pre-B-ALL at high frequency by reducing the expression of known tumor suppressors, including SPI-B, IKAROS, and BLNK." (PMID 29593731, 2018). "IRF8 upregulation was detected in DLBCL tumor tissues, and it was associated with decreased DLBCL patient survival." (PMID 28537908, 2017). "More interestingly, the cooperativity of IRF8 was markedly associated with tumor progression and even contributed to the patient survival independent of tumor stage." (PMID 27496222, 2016). "Loss-of-function experiments confirmed a causal role for IRF8 expression in regulating tumor growth in vivo." (PMID 26008967, 2015). "We previously showed that IRF8-loss enhanced tumor growth, which was accompanied by reduced tumor-cell susceptibility to apoptosis." (PMID 26008967, 2015). "We found that IRF8-loss significantly enhanced tumor growth rate compared to the vector control cells." (PMID 26008967, 2015). "The relevance of this IRF8-MMP3 axis in tumor growth in vivo was exemplified by the finding that knockdown of MMP3 expression significantly abrogated the enhanced tumor growth effect caused by IRF8-loss." (PMID 26008967, 2015). "We demonstrated that loss of IRF-8 expression led to a concomitant loss of Fas sensitivity to TSA-treated tumor cells in vitro." (PMID 23028998, 2012). "These new findings extend our previous work showing that tumor cell susceptibility to Fas-based effector mechanisms was IRF-8-dependent in vivo." (PMID 23028998, 2012). "Moreover, TRIM63, an E3 ubiquitin ligase, ultimately associates with IRF-8 resulting in degradation of the tumor suppressor gene to promote tumor progression." (PMID 41315179, 2025). "Low levels of IRF-8 have been strongly associated with tumor immunosuppression." (PMID 41315179, 2025). "Interestingly, in HCC cells, IRF8 overexpression demonstrated enhanced antitumor effects by potentially regulating tumor-associated macrophages and T cell levels in the tumor microenvironment." (PMID 38999981, 2024). "IRF8 expression sensitized the metastatic tumor cells to Fas-mediated apoptosis, indicating that loss of IRF8 in cancers could promote earlier metastasis." (PMID 36078039, 2022). "When gene expression profiles were compared between tumor-derived GPs and IRF8 KO GPs, shared expression profiles indicated that loss of IRF8 may underlie the formation of GPs and subsequent PMN-MDSC formation in tumors." (PMID 36078039, 2022).